SMAD2 (SMAD family member 2)
Diseases named in the same sentence as SMAD2 in open-access papers (continued):
Sharing a sentence is not in itself a finding about the gene and the disease.
asthma (26 papers, 2007 to 2025). "The SMAD2 gene encodes a cofactor involved in regulation of the growth factor β signaling that has been extensively evidenced to play a key role in asthma." (PMID 30805318, 2019). "We hypothesize that the cleavage of Nup153 in RV infection leads to accumulation of TGF-β induced SMAD2 in the nucleus and sustained AR associated gene expression, essentially priming the airway to increased risk of asthma in later years." (PMID 38249483, 2023). "TGFβ1 signaling is mediated intracellularly via the phosphorylation and subsequent nuclear translocation of SMAD2/3 transcription factors, and both genome-wide association and epigenetic studies have identified associations between components of the TGFβ1 signalling pathway and asthma risk." (PMID 34367159, 2021). "Inhibition of TGF-β1-induced activation of the Smad2/3 pathway and MAPKs, as well as amelioration of epithelial damage and subepithelial fibrosis in the airways in a mouse model of asthma, were also confirmed." (PMID 39120302, 2024). "Antifibrotic TGF-β/Smad1 pathway activation is downregulated in fibroblasts; however, profibrotic TGF-β/Smad2/3 pathways are upregulated in patients with asthma." (PMID 37569643, 2023). "The results of this study highlighted the fact that miR‐124‐3p is associated with EMT and asthma progression and functions by suppressing the activation of the TGF‐β1/Smad2 signaling pathway by negatively regulating S100A4." (PMID 36799806, 2023). "RT‐qPCR and western blot analysis showed that the expression levels of TGF‐β1 and Smad2 in lung tissues of mice in the model group were elevated (p < .01, vs. sham group), indicating that asthma can activate the TGF‐β1/Smad2 signaling pathway." (PMID 36799806, 2023). "The TGF‐β1/Smad2 signaling pathway was previously reported to be involved in asthma‐related fibroblast‐to‐myofibroblast transition." (PMID 36799806, 2023). "In our study, EP300, ID1, ID3, SMAD2, and SMAD5 were DC with a loss of connectivity, whereas SMAD7 exhibited a network connectivity gain due to asthma." (PMID 34257337, 2021). "In the murine study model, it was shown that the antibody of TGF-β1 prevents phosphorylation of Smad2 in prolonged allergen challenge-induced asthma." (PMID 32155894, 2020). "Previously, we showed the impact of statins and methylxanthines on the attenuation of the TGF-β1/Smad2 signaling axis in HBFs derived from asthma patients." (PMID 30158495, 2018). "Additionally, the use of the DEK-targeting aptamer DTA-64 has been shown to reduce OVA-induced airway remodeling in asthma through the modulation of various signaling pathways such as Smad2/3, Smad4, p38MAPK, ERK1/2, JNK, and PI3K/AKT/mTOR." (PMID 38274803, 2023). "Moreover, it can inhibit the inactivation of Smad2/3 proteins to exert the effect of inhibiting asthma airway remodeling." (PMID 36588723, 2022). "Additionally, some studies have shown that Sirt6 attenuates the EMT process in some diseases, such as suppressing the TGF-β1/Smad3 pathway and c-Jun in an asthma model or inactivating the TGF-β1/Smad2 pathway in bronchial epithelial cells." (PMID 34122724, 2021). "The aim of the present study was to evaluate whether enhanced asthma-related TGF-β1 FMT is the result of the differential activation of the profibrotic TGF-β/Smad2/3 and antifibrotic TGF-β/Smad1/5/9 signalling pathways in HBFs." (PMID 33020537, 2020). "Our data suggest that asthma induced Smad2/3 expression is inhibited by Nepeta bracteata Benth." (PMID 27073403, 2016). "However, antibody to TGFβ1 was shown to prevent phosphorylation of Smad2 in a murine model of prolonged allergen challenge-induced asthma." (PMID 17892594, 2007). "In this study, we evaluated the effects of stigmasterol on inflammatory cytokines and the TGF-β1/Smad2 and IL-17A signaling pathway in an ovalbumin (OVA)-induced asthma mouse model." (PMID 38579176, 2024).
asthma (continued). "TGF-β1-mediated signaling pathways, such as Smad2/3, p38, ERK1/2, and JNK MAPK, play important roles in epithelium injury and the EMT process in asthma." (PMID 35368934, 2022). "We hypothesize that RV infection leads to increased nuclear SMAD2, resulting in sustained TGF-β induced gene expression, priming the airway for subsequent development of asthma." (PMID 38249483, 2023). "However, it is noteworthy to mention that this increased pSmad2 observed in asthma does not exclude the possible involvement of other TGFβ family members in the activation of AR-Smads (Smad2/3)." (PMID 17892594, 2007). "In this study, we showed that osthole could inhibit the activation of TGF-β1/Smad2/3 and ERK1/2, p38, JNK MAPK signaling, thus contributing to the suppression of EMT and cell apoptosis in airway epithelium, respectively, in the experimental asthma model in vitro and in vivo." (PMID 35368934, 2022). "It is not clear whether dictamnine modulates asthma-related signaling pathways, particularly TGF-β/Smad2/3 signaling." (PMID 41465320, 2025).
osteosarcoma (26 papers, 2015 to 2025). A usually aggressive malignant bone-forming mesenchymal neoplasm, predominantly affecting adolescents and young adults. "Additionally, VCP has been implicated in promoting EMT through the TGF-β1/Smad2/3 signaling pathway, while its inhibition attenuates osteosarcoma cell invasion and metastasis." (PMID 39802400, 2025). "According to previous studies, GLA can inhibit epithelial-mesenchymal transition in osteosarcoma by restraining TGF-β1/Smad2/3 signal transduction pathway, so as to achieve the effect of treating osteosarcoma." (PMID 38500177, 2024). "Then, downregulated DIO3OS expression significantly inhibited the phosphorylation of SMAD2 in osteosarcoma cell lines." (PMID 37752544, 2023). "Since the phosphorylation of Smad2 and Smad3 plays a pivotal role in TGFβ signaling, we tested the phosphorylation level of Smad2 and Smad3 after treating osteosarcoma cells with gradient concentrations of AMTB." (PMID 35361751, 2022). "A recent study has found that the overexpression of p-Smad2, p-Smad3, and Smad4 increased caspase 3 and caspase 9 activation in osteosarcoma cells." (PMID 32126993, 2020). "Finally, we added TGFβ (5 ng/ml) to AMTB-treated osteosarcoma cells and observed that the phosphorylation level of Smad2 and Smad3 was rescued to basal level." (PMID 35361751, 2022). "miR-548c-3p negatively regulated SMAD2 in osteosarcoma cells." (PMID 33511320, 2021). "SMAD2 transcriptionally upregulated LINC00266-1 in osteosarcoma cells." (PMID 33511320, 2021). "Activation of Smad2/3 or inhibition of Akt may represent a promising approach for the targeted therapy for osteosarcoma." (PMID 32126993, 2020). "We deliver strong evidence that osteosarcoma cell-derived EVs can induce lung fibroblast reprogramming and thereby direct fibroblast activation and differentiation towards a myofibroblast/CAF phenotype through EV-associated TGFβ1 and SMAD2 pathway activation." (PMID 32751693, 2020). "Moreover, significant expressions of CD42b, TF, TGF-β, Smad2/3, and p-Smad2/3 were also detected in a biopsy sample from an osteosarcoma patient compared with control." (PMID 32982740, 2020). "The interaction between EFEMP1 and STEAP1 facilitates the initiation of Wnt/β-catenin and TGF-β/Smad2/3 axes, leading to the induction of EMT, thereby promoting the infiltration and migration of osteosarcoma cells." (PMID 39822989, 2025). "Inhibiting SRC activated by TGF-β1 impaired the activation of ERK, Smad2, and Smad3, as well as Smad nuclear translocation, which, in turn, inhibited the induction of CTGF in rat osteosarcoma osteoblast-like cells." (PMID 38167009, 2024). "The results showed that the phosphorylation of SMAD2 was downregulated in osteosarcoma cells transfected with si-DIO3OS and the total SMAD2 expression remained unchanged." (PMID 37752544, 2023). "MiR‐542‐3p inhibits invasion and migration of esophageal cancer by repressing OTUB1, suppresses the proliferation of osteosarcoma via targeting Smad2, inhibits progression of oral squamous cell carcinoma by impeding ILK/TGF-β1/Smad2/3." (PMID 35427373, 2022). "Another example is candidate microRNA 2, predicted to bind SMAD2 and SMAD4, genes already related with Osteosarcoma, and resulting potentially interesting for further in vitro studies." (PMID 31816885, 2019). "Interestingly, PLK1 silencing markedly increased Smad2 and Smad3 phosphorylation in both MG‐63 and U2OS osteosarcoma cell lines." (PMID 38780513, 2024). "Meanwhile, the levels of TGFB2, p-Smad2, p-Smad3, and BMP-6 showed a reverse trend after the SRI-011381 application, suggesting that PNO1 could influence the progression of osteosarcoma cells via the TGF-β signaling pathway." (PMID 38071381, 2023). "Importantly, caspase 3 activation and p-Smad2/3 phosphorylation in osteosarcoma cells were significantly induced by curcumin and DMC resulting in apoptosis of caspase-mediated osteosarcoma cells." (PMID 34671398, 2021).
osteosarcoma (continued). "We further demonstrated that exosomal RNAs including Annexin2, Smad2, MTAP, CIP4, PEDF, WWOX, Cdc5L, P27, could also discriminate good and poor chemotherapeutic response for osteosarcoma treatment." (PMID 29100284, 2017).
diabetic nephropathy (25 papers, 2016 to 2026). "It alleviates diabetic nephropathy by inhibiting TGF-β1/Smad2/3 fibrotic pathways and ferroptosis, shields retinal cells via anti-apoptotic mechanisms (Bcl-2↑/Bax↓), and preserves testicular function through autophagy activation." (PMID 41001671, 2025). "Berberine (isoquinoline alkaloid; found in Coptidis Rhizoma and Cortex Phellodendri) had anti-fibrosis effects via inhibition of Smad2/3 in streptozocin-induced diabetic kidney disease model." (PMID 40354602, 2025). "Several studies have demonstrated that TGF-β1/Smad2/3 signaling is highly activated in diabetic nephropathy kidneys." (PMID 32143429, 2020). "Immunohistochemical staining showed increased phosphorylation of Smad2/3 in mice with diabetic nephropathy (DN+DMSO) when compared to the control group (Control), which was suppressed by TRAM34 (P<0.01)." (PMID 29425253, 2018). "In addition, PS-MPs promote the progression of inflammation and fibrosis in diabetic nephropathy through the TGF-β1/Smad2/3 signaling pathway." (PMID 39200182, 2024). "We have shown in this study TRAM34 normalized the expression of TGF-β1 and phosphorylation of Smad2/3 in the mice kidneys with diabetic nephropathy, which indicates TRAM34 repaired diabetic kidney damage partially through inhibiting the TGF-β1 signaling pathway." (PMID 29425253, 2018). "In recent years, it has been shown that TGF-β/Smad2 is downstream of AGT and is involved in fibrosis in diabetic nephropathy." (PMID 40362266, 2025). "As part of the TGF-β1 pathway, SMAD proteins, particularly SMAD2, SMAD3, SMAD4, and SMAD7, are crucial in diabetic nephropathy." (PMID 38972889, 2024). "CrPic administration was thus found to ameliorate diabetic nephropathy in SD rats via an antioxidative stress mechanism, as well the ability to inhibit TGF-β1/Smad2/3 expression." (PMID 32143429, 2020). "In diabetic nephropathy, LCN2 depletion aggravates disease progression by increasing oxidative stress and inflammation through activating small mothers against decapentaplegic (Smad2/3) signaling." (PMID 39512683, 2024). "Eight weeks of CrPic supplementation was found to repair renal function and reverse renal pathological changes (renal interstitial fibrosis and glomerular sclerosis) in diabetic nephropathy rats by an antioxidative stress mechanism, as well as by inhibiting TGF-β1 and Smad2/3 expressions." (PMID 32143429, 2020). "Smad2 and Smad3 are activated in kidneys of patients with CKD and experimental animals of unilateral ureteral obstruction (UUO), 5/6 nephrectomy, hypertensive nephropathy and diabetic nephropathy." (PMID 32957963, 2020). "Strikingly, the protein levels of TGF-β1, phosphor-Smad2, Smad4, and Smad7 were reversed after 8-weeks treatment with ergosterol, indicating that ergosterol can inhibit the renal TGF-β1/Smad2 signaling pathway in STZ-induced diabetic nephropathy mice." (PMID 30823598, 2019). "To determine whether the TGF-β1/Smad2/3 signaling pathway is an essential intermediary in KCa3.1 mediated diabetic nephropathy, we examined the effects of KCa3.1 on the expression of TGF-β1 in kidneys of mice with established diabetic nephropathy using real-time PCR and immunohistochemical staining." (PMID 29425253, 2018).
non-small cell lung carcinoma (25 papers, 2014 to 2025). A group of at least three distinct histological types of lung cancer, including non-small cell squamous cell carcinoma, adenocarcinoma, and large cell carcinoma. "The lncRNA OSER1-AS1promotes the deterioration of non-small cell lung cancer by sponging microRNA‐433‐3p to further increase Smad2 expression." (PMID 34101736, 2021). "In non-small-cell lung carcinoma (NSCLC), cancer metastasis was associated with inactivation of SMAD2-mediated and activation of SMAD3-mediated transcriptional programs." (PMID 32746934, 2020). "Mir-132 directly silences ZEB2, thus attenuating EMT, invasion and metastasis in colorectal and lung cancers, and reduces EMT and migratory/invasive capacity of human non-small cell lung carcinoma (NSCLC) through the EMT-related TGF-β1/Smad2 pathway." (PMID 28792442, 2017). "The immunohistochemical expression of p-Smad2 was evaluated in 78 formalin-fixed paraffin-embedded surgical resection specimens from clinical stage I to IIIA non-small cell lung cancer." (PMID 25373709, 2014). "The results suggested that high p-Smad2 expression in stromal fibroblasts predicted poor survival in patients with clinical stage I to IIIA non-small cell lung cancer." (PMID 25373709, 2014). "Additionally, miR-486-5p suppresses non-small cell lung cancer by targeting the TGF-β/SMAD2 signaling." (PMID 35251709, 2022). "Furthermore, a recent study demonstrated that TGFβ induced PD-L1 in vitro on human non-small cell lung cancer cell lines by Smad2-mediated canonical TGFβ signaling." (PMID 36338975, 2022). "Therefore, we investigate the expression of p-Smad2 in surgical resection specimens from non-small cell lung cancer, and evaluate the prognostic significance of p-Smad2 expression in stromal fibroblasts and cancer cells for patients with clinical stage I to IIIA non-small cell lung cancer." (PMID 25373709, 2014). "SAB inhibited non-small cell lung cancer A549 cells by inactivating MAPK and SMAD2/3 signaling pathways." (PMID 38398656, 2024). "The increased stability of LncRMRP due to m6A modification activates the SMAD2/SMAD3 pathway by enhancing TGFBR1 transcription, ultimately accelerating non-small cell lung cancer (NSCLC) progression." (PMID 36854773, 2023). "The stability of lncRNA RMRP is enhanced through m6A modification, regulating the TGFBR1/SMAD2/SMAD3 pathway and the proliferation and progression of non-small cell lung cancer." (PMID 35585970, 2022). "On the other hand, exposure to BPS has been shown to promote the migration of human non-small cell lung cancer cells through ERK1/2, mediated by the transforming growth factor β (TGF-β)/Smad-2/3 signalling pathway." (PMID 36011004, 2022). "To illustrate, in non-small cell lung cancer, METTL3-mediated m6A modification could enhance the stability of methylated lncRNA-RMRP transcripts, which further promotes TGFBR1 transcription and the activation of TGFBR1/SMAD2/SMAD3 signaling pathway." (PMID 40089501, 2025). "RMRP is upregulated in non-small cell lung cancer (NSCLC) and promotes proliferation, invasion, and migration by interacting and recruiting YBX1 to the TGF-β receptor 1 (TGFBR1) promoter, upregulating TGFBR1 and enhancing the TGFBR1/SMAD2/SMAD3 growth signaling pathway." (PMID 36754845, 2023).
atherosclerosis (23 papers, 2010 to 2025). A disease characterized by the build-up of fatty material and calcium deposition in the arterial wall resulting in partial or complete occlusion of the arterial lumen. "The pathogenesis of atherosclerosis is associated with two major signaling pathways: TGF-β1/Smad2/3 and TGFβ1/TAK1/Nf-κB." (PMID 41154653, 2025). "In vitro experiments confirmed that BYHWD can reverse the inhibition of the Foxp3/TGF-β/Smad2 pathway caused by blockers, thereby promoting Treg differentiation and improving atherosclerosis." (PMID 41458964, 2025). "Under hyperglycolytic conditions, abnormal acetate production increases acetyl-CoA levels through ACSS2, promoting TGF-β/Smad2/4 acetylation and the EndoMT, which contribute to the development of atherosclerosis." (PMID 40890841, 2025). "In this study, we demonstrated that USF1 transcriptionally activated USP14 to restrain NLRC5 degradation, which prompted atherosclerosis by facilitating EndMT by activation of Smad2/3 pathway." (PMID 38424494, 2024). "Collectively, these data demonstrated that activating Smad2/3 pathway was considered the downstream of USP14/NLRC5 axis to contribute to atherosclerosis progression by promoting EndMT in vivo." (PMID 38424494, 2024). "Taken together, we uncover a USF1/USP14/NLRC5/Smad2/3 axis that drives atherosclerosis progression via inducing EndMT." (PMID 38424494, 2024). "Although the TGFβ-Smad2/3 pathway plays a central role in EndMT, the mechanoreceptor responsible for activation of EndMT in atherosclerosis-prone regions of arteries was elusive." (PMID 34244146, 2021). "More importantly, the clinical findings were consistent with in vitro results, and SNHG16 and Smad2 mRNA were up‐regulated and miR‐205 was down‐regulated in the plasma from patients with atherosclerosis." (PMID 31441592, 2019). "To further confirm the role of SNHG16 in the involvement of CVDs, we determined the expression levels of SNHG16, miR‐205 and Smad2 in the plasma samples from healthy volunteers and patients with atherosclerosis." (PMID 31441592, 2019). "The potential mechanism of preventing restenosis was to inhibit atherosclerosis formation and to attenuate intimal hyperplasia by downregulating Smad2/3 phosphorylation and TGF-β1 expression, promoting eNOS activity." (PMID 29922218, 2018). "Additionally, USF1 transcriptionally activated USP14 to drive atherosclerosis by promoting EndMT through the NLRC5/Smad2/3 axis." (PMID 40413536, 2025). "This is accompanied by enhanced Smad2/3 phosphorylation to promote the EndMT and atherosclerosis." (PMID 40890841, 2025). "EVs from subcutaneous adipose tissue stem cells and bone marrow mesenchymal stem cells, loaded or not with Smad2/3-siRNA, ameliorated vascular dysfunction and reduced atherosclerosis-associated inflammation in an experimental animal model of atherosclerosis." (PMID 36830690, 2023). "The findings signify that adropin treatment may alleviate the atherosclerosis in ApoE–/–/Enho–/– mice by inhibiting EndMT via the TGF-β/Smad2/3 signaling pathway." (PMID 37903785, 2023). "Moreover, SNHG16 and Smad2 mRNA were up‐regulated, while miR‐205 was down‐regulated in the plasma from patients with atherosclerosis." (PMID 31441592, 2019). "The Smad2 linker region is also associated with other pathophysiological conditions which include but are not limited to proteoglycan synthesis and GAG chain elongation associated with atherosclerosis development." (PMID 28719611, 2017).